ABCG5 (ATP binding cassette subfamily G member 5)
Diseases named in the same sentence as ABCG5 in open-access papers (continued):
Sharing a sentence is not in itself a finding about the gene and the disease.
sitosterolemia (continued). "Sitosterolemia (STSL) is a rare, autosomal recessive disease caused by mutations in the genes ABCG5 (encoding sterol-1) and ABCG8 (encoding sterol-2) located on chromosome 2p21." (PMID 35743896, 2022). "Since these rat strains are also know to carry mutations at other genetic loci and the extent of phytosterolemia is only moderate, it is important to verify that the mutations in Abcg5 are causative for phytosterolemia and whether they contribute to hypertension." (PMID 16026620, 2005). "Three variants, ABCG5: c.1573C>T and ABCG8: c.687G>A and c.1757-2A>G, were previously identified by Invitae in sitosterolemia patients who were part of this study." (PMID 39860331, 2025). "Fourteen variants were detected, nine in ABCG5 and five in ABCG8, with five variants reported for the first time in sitosterolemia patients." (PMID 39860331, 2025). "Mutations in ABCG5 or ABCG8 lead to increased intestinal absorption and decreased biliary excretion of plant sterols and cholesterol, resulting in sitosterolemia." (PMID 39860331, 2025). "A genetic study can be conducted to analyze DNA mutations in the ABCG5 or ABCG8 gene and confirm the diagnosis of sitosterolemia." (PMID 39055399, 2024). "Mutations in the ATP-binding cassette subfamily G members 5 and 8 (ABCG5 and ABCG8, respectively) genes have been associated with sitosterolemia, an autosomal recessive disorder characterized by increased plant sterol levels." (PMID 37137823, 2023). "In humans with a rare genetic disorder known as sitosterolemia (OMIM 210250), mutations in either ABCG5 or ABCG8 genes result in loss of biliary sterol secretion and toxic accumulation of plant sterols in the body." (PMID 34117281, 2021). "Transcriptional regulation of Abcg5 Abcg8 by a small molecule LXR agonist (T0901317) precipitated its discovery as the defective gene in sitosterolemia." (PMID 33807969, 2021). "Our previous work demonstrated that phytosterolemia induced by feeding ABCG5/8 double knockout (DKO) mice a phytosterol enriched diet led to cardiac fibrosis and death." (PMID 34465831, 2021). "An observation from inherited disease patients with ABCG5 and/or ABCG8 deficiency presented sitosterolemia and premature coronary disease." (PMID 33801029, 2021). "Frameshift mutations in exon 13 of both ABCG5 and ABCG8 cause sitosterolemia, indicating little tolerance for truncation of the protein." (PMID 33807969, 2021). "Three independent mouse models of sitosterolemia have been developed which lack functional Abcg5, Abcg8, or both half transporters." (PMID 33807969, 2021). "We believe that genetic analyses for ABCG5/ABCG8 gene are useful not only to identify carriers of sitosterolemia (patients with hyper LDL cholesterolemia), but also to select the additional therapies for further LDL reduction on top of statins." (PMID 31901240, 2020). "Massively parallel sequencing results showed variants in the ABCG5 gene (NM_022436.2) for HC1 and ABCG8 gene (NM_022437.2) in HC2, both of which are known causative genes for sitosterolemia." (PMID 32845916, 2020). "Genetic variation in ABCG5 and ABCG8 has been associated with sitosterolemia while GWAS has recently implicated SORT1 as a novel locus for LDL cholesterol." (PMID 24503134, 2014). "This is the case of subjects affected by sitosterolemia or mice with deletions of Abcg5/Abcg8 genes." (PMID 23951193, 2013). "Mutations in two adjacent ATP-binding cassette transporters, ABCG8 (sterolin-2) and ABCG5 (sterolin-1) that regulate sterol transport at the apical surface of hepatocytes and enterocytes have been identified in patients with sitosterolemia." (PMID 23675242, 2011). "Notably, five variants, including ABCG5: c.403-2A>T and c.1573C>T, and ABCG8: c.382A>T, c.687G>A, and c.1757-2A>G, were documented for the first time in sitosterolemia patients." (PMID 39860331, 2025).
sitosterolemia (continued). "Our study shows that ABCG5/8 could be underestimated in pediatric patients with hypercholesterolemia and NGS has an advantage in diagnosing sitosterolemia or carriers of ABCG5/8 gene comparing to gene panels of FH." (PMID 36991406, 2023). "First, ABCG5/G8 mutations resulted in autosomal recessive sitosterolemia; however, we did not measure sitosterol levels." (PMID 36981027, 2023). "Mutations in different genes have been shown to cause monogenic dyslipidemia, including LDLRAP1 mutations that are involved in autosomal recessive hypercholesterolemia, ABCG5/ABCG8, involved in sitosterolemia, or LMF1, which is associated with familial chylomicronemia syndrome." (PMID 37887310, 2023). "Mutations in the ABCG5 and ABCG8 genes are associated with pathological changes in sitosterolemia." (PMID 36937651, 2023). "At virtually the same time, independent groups identified individuals in multiple kindreds harboring nonsense mutations in either ABCG5 or ABCG8 with sitosterolemia, but not their unaffected family members." (PMID 33807969, 2021). "Two genes, ABCG5 and ABCG8, comprise the STSL and mutations in either cause sitosterolemia." (PMID 16507104, 2006). "To investigate whether the missense change in Abcg5 is responsible for the sitosterolemia we performed a segregation analysis in 103 F2 rats from a SHR × SD cross." (PMID 16026620, 2005). "Mutations of the ABCG5 (encodes sterolin-1) and ABCG8 (encodes sterolin-2) genes located on chromosome 2p21 cause sitosterolemia (STSL)." (PMID 37510094, 2023). "At the same time, the effect of dietary PS intake on plasma LDL-C lowering in heterozygotes for phytosterolemia is comparable to that of non-genetically affected individuals and can even be significantly higher in the presence of certain mutations in the ABCG5/G8 and NPC1L1 genes." (PMID 36839186, 2023). "While alterations in the ABCG5/8 genetic locus (sitosterolemia locus (STSL)) have been widely associated with sitosterolemia, there is a question of whether changes in ABCG5 and ABCG8 transporters might cause a higher susceptibility to other diseases such as cancer." (PMID 33805921, 2021). "Of note, serum sitosterol levels in heterozygous ABCG5 or ABCG8 variant carriers are increased by at most 2-fold, which is modest compared to the at least 50-fold increases usually observed in patients with sitosterolemia caused by homozygous or compound heterozygous variants." (PMID 33014402, 2020). "We hypothesized that hypercholesterolemic patients with a mutation in ABCG5 or ABCG8 gene exhibit better response to ezetimibe than those without, based on the fact that ezetimibe is hyper-effective for in patients with sitosterolemia caused by ABCG5 or ABCG8 genetic mutations." (PMID 31901240, 2020). "Besides, mutations in the gene ABCG5 and ABCG8 could cause sitosterolemia, which may lead to misdiagnosis of FH because of similar phenotypes." (PMID 30400955, 2018). "Sitosterolemia (OMIM#210250), is a very rare inherited sterol storage disease caused by mutations in the adenosine triphosphate-binding cassette (ABC) transporter genes ABCG5 and ABCG8, which are located on chromosome 2p21 and expressed at the membrane of enterohepatic cells." (PMID 25424010, 2014). "This study shows that the previously identified Gly583Cys change in Abcg5 in three hypertension-susceptible rats is responsible for the sitosterolemia, but may not be a major determinant of blood pressure in these rats." (PMID 16026620, 2005). "TNFa, TIMP-1, KC/GRO were all significantly elevated for the ABCG5/8 DKO group, consistent with phytosterolemia eliciting an inflammatory response triggering fibroblast activation and fibrosis." (PMID 34465831, 2021). "Thus, the remaining 1 potential sitosterolemia patient and 12 possible heterozygote carriers of ABCG5 or ABCG8 variants could not receive molecular confirmation." (PMID 32845916, 2020).
sitosterolemia (continued). "ABCG5 and ABCG8, originally referred to as sterolin‐1 and‐2, were first identified in patients with the rare genetic disease sitosterolemia, a disorder of sterol absorption and secretion that elevates plant sterol levels in plasma and tissues." (PMID 32978801, 2020). "The ABCG5 and ABCG8 genes are co‐expressed from a common promoter located on chromosome 2p21 at the STSL (sitosterolemia) locus in a head‐to‐head orientation." (PMID 32978801, 2020). "In this regard, ABC transporters, such as ABCA1, ABCG5 and ABCG8, were initially found to be responsible for genetically-inherited syndromes like Tangier diseases and sitosterolemia." (PMID 28383515, 2017). "The ABCG5 and ABCG8 genes are located at the sitosterolemia locus on chromosome 2p21." (PMID 38509578, 2024). "Therefore, genetic testing of the ABCG5 and ABCG8 genes will play a crucial role in the accurate and early diagnosis of sitosterolemia." (PMID 33014402, 2020). "Mutations in ABCG5 or ABCG8, comprising the sitosterolemia locus, STSL, are now known to cause this disease." (PMID 16026620, 2005). "Based upon the defects in sitosterolemia, ABCG5 and ABCG8 serve specifically to exclude non-cholesterol sterol entry at the intestinal level and are involved in sterol excretion at the hepatobiliary level." (PMID 15383151, 2004). "However, as no other ABCG5 or ABCG8 mutations were identified, the presence of sitosterolemia (autosomal recessive inheritance) was rejected." (PMID 35741760, 2022). "In sitosterolemia, lack of ABCG5/ABCG8 function leads to significantly greater absorption of dietary cholesterol and sitosterol and an increased incidence of cardiovascular events independent of plasma LDL-C levels, suggesting that sitosterol itself may be contributing to atheroma formation." (PMID 22649448, 2012).
gallstones (26 papers, 2009 to 2025). Solid crystalline precipitates in the biliary tract, usually formed in the gallbladder, resulting in the condition of cholelithiasis. "Regional association analyses in participants with GWAS Array data were performed to determine the peak association of genetic variants around the ABCG5/G8 region with lipid profile and gallstone disease history." (PMID 36981027, 2023). "Among four ABCG5/G8 variants associated with gallstone disease history, only two were nonsynonymous [ABCG5 R50C (rs6756629) and ABCG8 D19H (rs11887534)]." (PMID 36981027, 2023). "Because both the selected ABCG5/G8 variants and the lead SNPs were associated to various degrees with lipid profile and gallstone disease history, we further tested the LD between all these variants." (PMID 36981027, 2023). "Subsequently, ABCG5/G8 was found to be associated with cholesterol gallstone disease in patients, and two gallstone associated variants in ABCG5/G8 (ABCG5-R50C and ABCG8-D19H) were identified in Germans, Chileans, Chinese, and Indians." (PMID 35454138, 2022). "Genome wide association study of gallstone patients and linkage study of affected sibs presented important polymorphisms in ABCG5/8 and CCKA-R genes that participate in susceptibility to gallstone disease." (PMID 29511480, 2017). "Further studies on the functional contribution of these polymorphisms to the difference of ABG8 and ABCG5 function in cholesterol transportation will provide more information on their roles to promote gallstone formation." (PMID 24498041, 2014). "Moreover, a genetic variant recently has been identified (p.D19H) of the hepato-canalicular cholesterol transporter ABCG5/ABG8 as genetic risk factor for gallstones." (PMID 38996112, 2024). "In addition to weight loss, our study revealed that MIC-1 contributes to gallstone formation through ABCG5/8 overexpression." (PMID 37310967, 2023). "A further longitudinal study using healthy individuals carrying D19H polymorphism in ABCG5/8 might clarify whether our findings are cause or consequence of gallstone formation." (PMID 32366946, 2020). "For example, increased activity of the sterol-transporter ABCG5/8 that has a direct role in promoting biliary cholesterol secretion and in reducing intestinal absorption of dietary cholesterol is expected to increase the risk of gallstones while lowering circulating cholesterol." (PMID 30504769, 2018). "Mechanistically, the in vitro findings indicate that the gallstone dissolution effect is driven by strong activation of the liver X receptor alpha (LXRα)–ABCG5/8 pathway, which plays a pivotal role in regulating cholesterol transport in the hepatocytes." (PMID 41011256, 2025). "Gallstone formation can be prevented by reducing biliary cholesterol secretion (through the downregulation of ABCG5/8) or increasing FXR expression, which increases biliary bile acid and phospholipid secretion (via BSEP and MDR2)." (PMID 37310967, 2023). "In animals, as determined through quantitative trait locus linkage analysis, Abcg5/g8 has been identified as the mouse gallstone gene, Lith9." (PMID 36981027, 2023). "In this study, we found that MIC-1 treatment induces gallstone formation by increasing ABCG5/8 expression and altering cholesterol and bile acid homeostasis." (PMID 37310967, 2023). "Subsequently, some clinical studies have revealed that ABCG5/G8 is also a human gallstone gene, LITH9, in European, Asian, and Chilean Hispanic populations." (PMID 35741809, 2022). "Hepatic mRNA expression of ABCG5/G8 genes in 182 patients with gallstone disease and 35 gallstone-free patients who underwent cholecystectomy were determined using real-time PCR." (PMID 24498041, 2014). "What is more, research suggests that FXR and the heterodimer ABCG5/ABCG8 are possible determinants of cholesterol gallstone formation in mice via quantitative trait locus analysis." (PMID 25107305, 2014).
gallstones (continued). "It is important to understand the link between the sterol transporters ABCG5/8 and NPC1L1 and intestinal cholesterol absorption as well as de novo synthesis in gallstone patients stratified according to 19H risk allele." (PMID 23406058, 2013). "Increased gallstone formation in these mice has been attributed to increased biliary cholesterol excretion resulting from upregulation of ABCG5/8 due to induction of the forkhead transcription factor FoxO1 and downregulation of BA synthesis." (PMID 22885388, 2013). "In a previous study, we observed that Chinese gallstone patients had an increased hepatic ABCG5/ABCG8 expression." (PMID 20144195, 2010). "For instance, mutation of ABCG5/G8 (ATP-binding cassette, sub-family G (WHITE), member 5/8) limits biliary excretion of sterols and alters susceptibility to gallstones and atherosclerosis." (PMID 19835623, 2009). "A higher prevalence of gallstone disease in identical twins and first-degree relatives in individuals with gallstone disease highlights the importance of searching for genes involved in biliary cholesterol secretion that are critical to gallstone formation, such as ABCG5/G8." (PMID 36981027, 2023). "Therefore, MIC-1 treatment supports weight loss but can induce gallstone formation due to AMPK activation and ABCG5/8 overexpression." (PMID 37310967, 2023). "Thirdly, from a basic pathophysiological perspective, in gallstone patients, Abcg5/g8 may be elevated expression by the role of gut microbiota or genetic variation." (PMID 36505391, 2022). "In the same way D19H variant of ABCG8 was attributed in gallstone formation neither T400K of ABCG8 nor Q604E of ABCG5." (PMID 29511480, 2017). "In our previous study, we found higher levels of hepatic ABCG5/ABCG8 and LXRa mRNA in gallstone patients, which could cause higher amounts of cholesterol to be delivered into the bile." (PMID 20144195, 2010). "The distinct up-regulation of genes Abcg5 and Abcg8 might implicate hypersecretion of cholesterol into bile and lead to gallstones formation." (PMID 19835623, 2009). "Similarly, patients with gallstones had increased ABCG5 and ABCG8 levels and decreased BSEP levels." (PMID 34445033, 2021). "Although some LXR targets in mice are not conserved in humans, these results revealed that LXRα promoted cholesterol transport from the liver to bile and gallstone formation by upregulating ABCG5 and ABCG8 expression levels, which might provide a new direction in the treatment of gallstones." (PMID 32382260, 2020). "To date, the xenobiotic substrates of Abcg5 and Abcg8 have been used for regulating gallstones formation and treatments of cardiovascular disease, whereas the limited protective mechanism may not confer the expected reduction in cardiovascular risks in hypercholesterolemic patients." (PMID 19835623, 2009). "As a result, the potential induction of gallstone formation by MIC-1, mediated by AMPK activation and ABCG5/8 overexpression, should be monitored during obesity treatments using MIC-1." (PMID 37310967, 2023). "Our study indicates that MIC-1 influences gallstone formation by increasing AMPK phosphorylation, reducing CYP7A1 and HMGCR expression, and increasing ABCG5 and ABCG8 expression." (PMID 37310967, 2023). "FMO3 loss or gain-of-function experiments in cholesterol fed mice demonstrated that TMAO induces ABCG5 and ABCG8 expression, and presumably increases bile cholesterol content to drive gallstone formation." (PMID 34445033, 2021). "Meanwhile, we also detected increased SR-BI protein expression, which is believed to be a ABCG5/8 independent cholesterol transporter localized in canalicular membranes and conducting biliary cholesterol secretion in physical condtion 7, while its exact role in gallstone development remains unclear." (PMID 34803510, 2021). "After administration of the LXRα agonist, the ABCG5 and ABCG8 expression levels were further increased, and the gallstone formation was also promoted." (PMID 32382260, 2020).
gallstones (continued). "Increased hepatic expression of ABCG5 and ABCG8 mRNA in gallstone patients has been reported, which represents the main defect leading to hyper-secretion of cholesterol in hepatocyte." (PMID 27203212, 2016). "Sinapic acid is proposed to modulate the expression of hepatic cholesterol transporters, including ABCG5, ABCG8, and LXRα, thereby promoting bile acid synthesis and facilitating cholesterol metabolism, which collectively contribute to a reduction in gallstone formation." (PMID 41011256, 2025). "Therefore, ABCG5 and ABCG8 are thought to play crucial roles in gallstone formation by regulating cholesterol secretion." (PMID 37310967, 2023). "Regarding sterol exporter ABCG8 and ABCG5, no significant changes in expression were apparent when stratified according to gallstones, also not within the different weight groups." (PMID 23406058, 2013). "Therefore, canalicular transporters for cholesterol (ABCG5/8), BAs (BSEP) and phosphatidylcholine (MDR3/Mdr2 in rodents) and their regulatory NRs are relevant for gallstone formation." (PMID 22885388, 2013). "Abca1, Abcg5 and Abcg8 belong to the family of ABC transporters, which can mediate secretion of excessive cholesterol into bile and play important roles in consequent gallstones or atherosclerosis." (PMID 19835623, 2009). "Therefore, the present study demonstrates a novel role of miRNA-223 in the gallstone formation by targeting ABCG5 and ABCG8 and elevating miRNA-223 would be a potentially novel approach to overcome the sternness of cholesterol gallstone disease." (PMID 34803510, 2021). "Furtherly, in a small group of Chinese non-obese normolipidemic gallstone patients, the upregulation of ABCG5/ABCG8 in gallstone patients is mediated by increased LXRalpha possibly, may contribute to the cholesterol supersaturation of bile and the formation of gallstone." (PMID 25107305, 2014). "Moreover, the expression of ABCG5/8 and its regulatory NR liver X receptor (LXR) was increased and correlated with cholesterol saturation in Chinese non-obese gallstone patients." (PMID 22885388, 2013). "Notably, ABCG5/8 and NPC1L1 expression was similar in gallstone carriers and controls regardless of p.D19H presence." (PMID 23406058, 2013).